RNY4P23 (RNY4 pseudogene 23)
Gene: Miscellaneous RNA gene on chromosome X (70,396,279 to 70,396,375, forward strand). Ensembl gene ENSG00000201377.
Homologues: Orthologues: chimpanzee Y_RNA (100% identical), macaque Y_RNA (98% identical). Paralogues in human: RNY4 (90% identical), RNY4P6 (88% identical), RNY4P3 (87% identical), Y_RNA (86% identical), RNY4P13 (85% identical), RNY4P25 (85% identical), RNY4P7 (85% identical), Y_RNA (85% identical), RNY4P19 (84% identical), Y_RNA (82% identical), RNY4P10 (81% identical), RNY4P14 (81% identical), and 89 more.